IL6 (interleukin 6)
Diseases named in the same sentence as IL6 in open-access papers (continued):
Sharing a sentence is not in itself a finding about the gene and the disease.
pulmonary edema (42 papers, 2012 to 2026). Accumulation of fluid in the lung tissues causing disturbance of the gas exchange that may lead to respiratory failure. "IL-6 can induce acute inflammatory response, promote the activation and aggregation of neutrophils, cause pulmonary edema, and lead to systemic inflammatory response." (PMID 31241712, 2019). "Inflammation may be influenced by fiO2 level, as reported by some authors investigating subjects exposed to hypoxia that showed pulmonary edema caused by inflammatory markers release, including interleukin-6 (IL-6) and protein C-reactive (CRP)." (PMID 38474303, 2024). "In addition, the increase of the ratio of W/D weight as a key indicator of the severity of pulmonary edema and the pro-inflammatory factor levels of IL-1β, IL-6, and TNF-α caused by PQ was reverted back by Andro." (PMID 37275765, 2023). "Myocardial failure and pulmonary edema are also common complications, with increased interleukin-6 levels contributing to myocardial depression." (PMID 40248523, 2025). "Proinflammatory cytokines such as IL-6, TNF-α, and IL-1β were found to be associated with brainstem encephalitis complicated by pulmonary edema in EV-A71 infections." (PMID 40377310, 2025). "In a male neonate with pulmonary edema, the cytokines IL-6, IL-8, IL-10, IL-13, IL-17, and IFN-γ rises sharply during the first few hours after birth and then decreases significantly." (PMID 35725416, 2022). "In these studies, SEV significantly improved the oxygenation of lung grafts and reduced pulmonary edema through the reduction of IL-1β, IL-6, and TNF-α." (PMID 33506025, 2021). "Improved oxygen saturation.Reduced lung inflammation and pulmonary edema.Reduced IL-6 and TNF-α levels." (PMID 32519302, 2020). "Reduced lung inflammation and pulmonary edema.A decrease in IL-1, IL-1 β, IL-6, and TNF-α levels.Restoration of Treg/Th17 balance." (PMID 32519302, 2020). "IL-6 and IL-13 levels are remarkably higher in patients with CNS infections and pulmonary edema with fatal outcomes than in uncomplicated patients." (PMID 29156632, 2017). "The main findings of this study are that VILI is associated with pulmonary edema, increased levels of BALF inflammatory cytokines IL-1β, IL-6, and RANTES, neutrophil counts, MPO activity, lung Rho activation, and ultrastructural damage of alveolar endothelium." (PMID 25019086, 2014). "A large number of cytokines, such as TNF-α and IL-6 release, lead to neutrophil aggregation in lung tissue, destruction of alveolar epithelial structure, ECM damage, and alveolar-capillary membrane injury, thereby causing exudative pulmonary edema." (PMID 32765635, 2020). "By inhibiting NF-κB–dependent transcription of pro-inflammatory cytokines (TNF-α, IL-1β, IL-6) and attenuating oxidative stress, deslanoside may help preserve alveolar–capillary barrier integrity, reduce endothelial permeability, and alleviate pulmonary edema." (PMID 41244837, 2025). "Previously published data have demonstrated in cases of high-altitude pulmonary edema, there is an increase in the infiltration of inflammatory cells, specifically macrophages and neutrophils, as well as elevated levels of cytokines such as IL-6, TNF-α, and IL-1β." (PMID 38166725, 2024). "Digoxin significantly reduced pulmonary edema in the therapeutic group (p = 0.02) and decreased TNF-α levels (p = 0.014), while robustly suppressing IL-6 and MDA in both prophylactic and therapeutic settings (each p < 0.001)." (PMID 41693482, 2026). "Both CNS (IL-1β, IL-6, IFN-γ, IP-10, MIG) and systemic inflammatory responses (IL-6, IL-8, IL-10, IL-13, IP-10, MCP-1, MIG) to infection play leading, but distinctly different, roles in the pathogenesis of EV71 pulmonary edema." (PMID 41035913, 2025). "TNF-α and IL-6 are important cytokines in the development of ALI, which can activate the endothelial cells and lead to pulmonary edema." (PMID 35281058, 2022).
pulmonary edema (continued). "Beta-sitosterol can significantly reduce LPS-induced pulmonary edema and inflammatory response and reduce the release of TNF-a and IL-6." (PMID 33335558, 2020). "One study indicated that patients with brainstem encephalitis and pulmonary edema exhibit elevated serum and CSF levels of IL-6, TNF-α, IL-1β, and IFN-γ, suggesting that pulmonary edema may result from increased vascular permeability due to systemic inflammation." (PMID 39767680, 2024). "Proinflammatory cytokines Interleukin (IL)-6, IL-8 and TNF are increased and directly injury the lung endothelium, leading to cardiogenic and non-cardiogenic pulmonary edema." (PMID 37724533, 2023).
Zinc deficiency (42 papers, 2009 to 2025). A deficiency of the essential metal Zinc; an essential cofactor for many enzymes. "Zinc deficiency is associated with increased production of proinflammatory cytokines, such as IL-6, TGF-β, and TNF-α." (PMID 41614883, 2025). "Zinc deficiency increases the proinflammatory cytokines’ production, such as IL-1β, IL-6, and TNF-α, as well as induces oxidative stress due to its scavenging properties against reactive oxygen species (ROS)." (PMID 41427149, 2025). "Non-invasive biomarkers, including magnesium and zinc deficiencies, inflammatory cytokines like interleukin-6 (IL-6), and salivary markers, such as cortisol, alpha-amylase, and secretory immunoglobulins, expand ADHD diagnostic tools." (PMID 41200630, 2025). "As a result of zinc deficiency, the production of some proinflammatory cytokines, such as IL-6, TGF-β, and TNF-α can increase." (PMID 41614883, 2025). "Chronic zinc deficiency in a chick model triggered a decrease in gene expression of pro-inflammatory cytokines (IL-1β, IL-6, TNF)." (PMID 35344152, 2023). "In SAM children, zinc deficiency has been linked to elevated levels of pro-inflammatory cytokines such as interleukin-6 (IL-6) and tumor necrosis factor-alpha (TNF-α)." (PMID 38068727, 2023). "Zinc deficiency predisposes people to infectious and inflammatory diseases and increases the production of pro-inflammatory cytokines: interleukin-6, interleukin-8, and tumor necrosis factor." (PMID 35330104, 2022). "In our previous work, LPS-induced IL-6 response in whole blood increased with zinc deficiency, and was further increased with age." (PMID 36534653, 2022). "Previously published studies underlined that zinc deficiency appears to promote the production of proinflammatory cytokines such as IL-1β, tumor necrosis factor alpha (TNFα), and IL-6 by myeloid cells and activated monocytes/macrophages." (PMID 34934131, 2021). "Zinc deficiency induces a progressive demethylation of the IL-6 promoter in THP1 cells, which correlated to increased IL-6 expression." (PMID 32754165, 2020). "Here, in vitro studies revealed that IL-4-induced STAT6 and IL-6-induced STAT3 phosphorylation were decreased during zinc deficiency." (PMID 29186856, 2017). "Diseases such as rheumatoid arthritis and plasma cell neoplasia go along with reduced serum zinc levels, indicating potential co-effects of IL-6 overproduction and enhanced susceptibility of B cells due to zinc deficiency." (PMID 29064429, 2017). "Zinc deficiency increases the production of proinflammatory cytokines, such as interleukins IL-1β, IL-6, and tumor necrosis factor (TNF)-α." (PMID 28629136, 2017). "Zinc deficiency increased IL-6-induced activation of JAK-STAT3 signaling pathways; reconstitution with zinc normalized the effect while zinc supplementation was shown to inhibit STAT3 phosphorylation induced by IL-6 and IL-1." (PMID 29064429, 2017). "Zinc deficiency influences the generation of cytokines, including IL-1β, IL-2, IL-6, and TNF-α, and in response to zinc supplementation plasma cytokines exhibit a dose-dependent response." (PMID 22852057, 2012). "Chronic low level inflammation is common in the elderly, and zinc deficiency impairs cytokine homeostasis in this population, leading to increased production of pro-inflammatory cytokines such as IL-6, which can be corrected by zinc supplementation." (PMID 19523191, 2009). "In addition, the reaction characterized by IL-6 and IL-2 stimulation caused by zinc deficiency enhances the proliferative responses of T and B lymphocytes." (PMID 40933952, 2025). "Additionally, zinc deficiency is seen to be inflammatory through the induction of IL6 promoter demethylation." (PMID 36557277, 2022). "IL-6 is also important for the induction of terminal B cell development into plasma cells, providing an additional reason for the decrease in antibodies during zinc deficiency." (PMID 36551176, 2022).
Zinc deficiency (continued). "Similarly, in vitro studies have shown that Zinc deficiency results in increased IL‐6, IL‐1β production, and increased expression of intercellular adhesion molecule 1 that helps in leukocytes' extravasation." (PMID 36239436, 2022). "In monocytes, zinc deficiency reduces the production of IL-6 and TNF-α." (PMID 33375344, 2020). "Zinc deficiency causes dysregulation of immune function, resulting in increased levels of inflammatory cytokines (i.e., interleukin-6 and tumour necrosis factor α), alongside deterioration of the antioxidant protection of cells and an increase in susceptibility to infection." (PMID 32294896, 2020). "This study also highlights that zinc deficiency is overestimated when the infants are in a condition with inflammation, which may be mediated by IL-6, etc.." (PMID 31443415, 2019). "Furthermore, zinc signals are important for IL-6 induced STAT3 phosphorylation shown to be increased due to zinc deficiency." (PMID 29064429, 2017). "IL-6 is essential for the induction of terminal B cell development into plasma cells, providing an additional reason for the decrease in antibodies during zinc deficiency." (PMID 29186856, 2017). "Moreover, zinc deficiency triggers the IL-6-induced phosphorylation of STAT3, thereby pathologically enhancing B cell differentiation into antibody-producing plasma cells and autoantibody production." (PMID 29186856, 2017). "Pre-existing zinc deficiency augmented the effect of IL-6-or IL-1-induced JAK-STAT3 signaling." (PMID 29186856, 2017). "However, the overall effects of zinc deficiency on the production of IL-6 and TNF-α remain unclear, as the results are inconsistent depending on the compound and the dose of cell-stimulation (e.g., lipopolysaccharide (LPS) vs. phytohaemagglutinin (PHA))." (PMID 33375344, 2020). "This oral supplementation also reduced the elevated serum levels of the pro-inflammatory cytokines IL-6 and TNF-α induced by zinc deficiency." (PMID 40871688, 2025). "Similar to our results, studies in both murine and human primary monocytes had shown zinc deficiency to impair TLR4-mediated signaling that resulted in reduced production of cytokines such as TNF-α, IL-6, IL-10, and Il-1β." (PMID 36558553, 2022). "Zinc deficiency also decreases the production of Th1 cytokines (TNF-α, IL-2, and IFN-γ), whereas the Th2 cytokine response (IL-10, IL-6, and IL-4) is less affected." (PMID 32944394, 2020). "Zinc deficiency resulted in activating monocytes-macrophages, which resulted in increased generation of inflammatory cytokines such as TNF-α, IL-1β, and IL-6 and increased oxidative stress." (PMID 32411807, 2020). "Decreases in body weight, growth hormone, dietary intake, thymic organ coefficient, IL-1/IL-6, thymosin, and insulin in LZG indicated that zinc deficiency negatively affected growth, immunity, and sugar metabolism in rats." (PMID 31687040, 2019). "During zinc deficiency, there is also reduced production of IFN-γ and IL-2, which are products of Th1 cells, while the production of IL-4, IL-6, and IL-10 (products of Th2 cells) remain unchanged." (PMID 28629136, 2017). "IL-6, the most important proinflammatory cytokine regulating the acute–phase protein production regulates ZIP14 in liver and contributes to the zinc deficiency of acute–phase response." (PMID 24548602, 2014). "The generation of a variety of cytokines, including IL-1β, IL-2, IL-6, and TNF-α, is reportedly influenced by mild to moderate zinc deficiency in humans." (PMID 22852057, 2012). "Zinc deficiency leads to the activation of monocytes/macrophages, which generate free radicals, causing oxidative stress and triggering the production of cytokines such as tumor necrosis factor (TNF-α), interleukin IL-1β, and IL-6." (PMID 38138191, 2023). "A large category of cytokines, including IL-4, IL-6, interferon-g (IFN-g), TNF-α from innate immunity, and IL-2, TNF, and IFN-γ from adaptive immunity were found to be inhibited in production in patients with zinc deficiency." (PMID 35211497, 2022).
Zinc deficiency (continued). "During zinc deficiency, studies reported an imbalance between Th1 and Th2 cell differentiation, resulting in a diminished Th1 immune response with lowered IFN-γ and IL-2 production, whereas the Th2 cytokines (IL-4, IL-6, and IL-10) remain unaffected." (PMID 36551176, 2022). "During zinc deficiency, the JAK-STAT3 signaling pathway is activated in an IL-6 dependent manner." (PMID 36551176, 2022). "Zinc deficiency in humans activates monocytes-macrophages, which generate free radicals leading to oxidative stress and upregulate generation of inflammatory cytokines such as TNF-α, IL-1β, and IL-6." (PMID 32411807, 2020). "Zinc deficiency can inappropriately enhance inflammatory responses; zinc deficiency was found to correlate with Il6 promoter demethylation in THP-1 cells, which led to increased IL-6 production and inflammation." (PMID 31214161, 2019). "Therefore, both CRP and serum albumin have been reported to be associated with elevated CRP, IL-6, TNF-α, IL-1β, and zinc deficiency." (PMID 30941358, 2019). "Zinc deficiency also augmented LPS-induced expression of IFNγ, CD80 and CD86 in murine macrophages either bone marrow-derived, or from cell culture, while expression of IL-1β, IL-6 and IL-10 was decreased." (PMID 29186856, 2017). "The presence of an immune response in zinc deficiency is proven through an increase of TNF-α and IL-6 level before intervention and conversely, the reduction in the immune response is characterized by a decrease in TNF-α and IL-6 level after zinc administration." (PMID 32148672, 2019). "For instance, zinc deficiency reduced production of Th1 cytokines, in particular IFN-γ, IL-2, and tumor necrosis factor (TNF)-α, whereas levels of Th2 cytokines IL-4, IL-6, and IL-10 were not affected." (PMID 29196724, 2017). "During zinc deficiency, the production of TH1 cytokines, in particular IFN-γ, IL-2, and tumor necrosis factor (TNF)-α is reduced, whereas the levels of the TH2 cytokines IL-4, IL-6, and IL-10 were not affected in cell culture models and in vivo." (PMID 19523191, 2009).
colorectal tumor (41 papers, 2002 to 2025). "As IL-6 is a protumorigenic cytokine that is highly elevated in colitis-associated neoplasias, we checked the correlation between Il-6 and Il-9 mRNA levels in colorectal tumours of wild-type mice." (PMID 35793807, 2022). "IL-6, secreted by MSCs, stimulates the growth of colorectal tumor-initiating cells and encourages tumor development through STAT3 signaling." (PMID 40534879, 2025). "Another study demonstrated that under normoxic conditions, exosomes from colorectal tumors stimulate interleukin-6 (IL-6) secretion by hepatic stellate cells within the metastatic liver microenvironment through the activation of p-ERK and p-AKT." (PMID 39403606, 2024). "Five studies reported elevated levels of IL-6, a pleiotropic pro-inflammatory cytokine, in patients with higher phenotypic and deficit accumulation frailty across the breast, prostate, and colorectal tumors." (PMID 37213604, 2023). "Pre-treatment levels of IL-6, TNF-α, and CRP were significantly associated with increased phenotypic frailty in colorectal tumors." (PMID 37213604, 2023). "JAK2 inhibitor CEP-33779 inhibited colorectal tumor growth by inhibiting IL-6/JAK2/STAT3 signal transduction." (PMID 36591515, 2022). "Interleukin-6-mediated activation of STAT3 in fibroblasts played a key role in driving colorectal tumors." (PMID 35211500, 2022). "PC also inhibited colorectal tumor proliferation, and alleviated colonic inflammation by decreasing the inflammatory cytokines (IFNγ and IL-6) level." (PMID 35447933, 2022). "Activation of IL-6/p-STAT3/c-MYC signaling was demonstrated to enhance colorectal tumor growth in a TLR4-dependent manner." (PMID 34898475, 2021). "To confirm further the results of the in vitro experiments, we used immunofluorescence to detect the expression of P-STAT 3, IL-6, Bcl-2, and Cyclin D1 in colorectal tumors." (PMID 33082817, 2020). "TNF-α and IL-6 are core cytokines in the colorectal tumor promotion by activating NF-κB signaling pathways and STAT3." (PMID 30157754, 2018). "The continuous evidence of recent years has convinced us that IL-6/JAK/STAT3 pathway can play a definitive role in the transformation from inflammation to cancer for colorectum tumor." (PMID 28061445, 2017). "Some studies have reported that IL-6 levels are higher in neutropenic CRC patients with advanced clinical staging, suggesting that IL-6 may be closely related to the altered biological properties of colorectal tumor cells." (PMID 39980561, 2025). "The ApcMin/+ mouse model, a noteworthy exemplar, manifests cancer cachexia hinges on systemic interleukin-6 (IL-6) and has been meticulously employed to emulate the progression of colorectal tumor development akin to human familial adenomatous polyposis (a condition affecting the colon and rectum)." (PMID 37755304, 2023). "Previous studies evaluating the effect of PN enriched with ω3 LE on the immune response of patients with gastric or colorectal tumors found significant differences between groups in reducing the inflammatory response, measured by parameters like IL-6, CRP, and TNF-α." (PMID 38201870, 2023). "It inhibits colorectal tumor growth by inhibiting IL-6/JAK2/STAT signal transduction." (PMID 36591515, 2022). "Interestingly, it has been recently described that HIF and IL-6 expression is increased in colorectal tumors, being both markers positively correlated." (PMID 32231135, 2020). "The AOM/DSS treated mice developed multiple colorectal tumors in the colon tissues, suggesting that TNF-α and IL-6 may be associated with tumor formation." (PMID 31694526, 2019). "In the present study, we investigated the role of 1,25D3, TNFα, and IL-6 on the transcriptional and translational activation of the CaSR in two cell lines representing a highly differentiated and a moderately differentiated colorectal tumor." (PMID 24176760, 2014). "Additionally, treatment of colorectal tumor cells with IL-6 potentiates the IFN-γ induction of HLA class II expression." (PMID 19497133, 2009).